PTTG1 (PTTG1 regulator of sister chromatid separation, securin)
Diseases named in the same sentence as PTTG1 in open-access papers (continued):
Sharing a sentence is not in itself a finding about the gene and the disease.
liver fibrosis (2 papers, 2022). "While little is known about its involvement in liver fibrosis, PTTG1 expression is associated with DLK1." (PMID 35050550, 2022). "Progression of liver fibrosis was associated with a concomitant increase in Pttg1 mRNA expression." (PMID 35050550, 2022). "Overall, our findings indicate that the PTTG1/DLK1 pathway is relevant in the pathogenesis of liver fibrosis." (PMID 35050550, 2022). "These authors studied the development of liver fibrosis induced by thioacetamide in knockout and wild type Pttg1 mice." (PMID 35805898, 2022). "In contrast, Pttg1 mRNA levels were markedly overexpressed in the liver of rats with hepatic fibrosis, reaching maximal abundance in cirrhotic rats." (PMID 35050550, 2022). "On the other hand, DLK1 has been identified as one of the most abundantly expressed PTTG1 targets in adipose tissue and has shown to contribute to hepatic fibrosis by promoting the activation of hepatic stellate cells." (PMID 35805898, 2022). "In summary, these findings further support the hypothesis that PTTG1/DLK1 signaling could be a novel pathway for targeting the progression of liver fibrosis." (PMID 35805898, 2022). "Our findings suggest that RNA‐based therapy targeting Pttg1, such as siRNA, may prevent the development of liver fibrosis." (PMID 35050550, 2022). "Several potential mechanisms mediate the effects of Pttg1 knockdown on hepatic fibrosis." (PMID 35050550, 2022). "PTTG1/DLK1 signalling is a novel pathway for targeting the progression of liver fibrosis." (PMID 35050550, 2022). "The present study shows that Mmp2 expression increases in liver fibrosis, however, Pttg1 interference may have an antifibrogenic effect also by reducing Mmp2 expression and, consequently, by blocking degradation of normal perisinusoidal matrix and promoting activation of quiescent HSC." (PMID 35050550, 2022). "Based on the concept that DLK1 is one of the most abundantly expressed PTTG1 targets, we recently documented the close link between DLK1 and PTTG1 in the progression of liver fibrosis." (PMID 35805898, 2022). "Thus, the PTTG1/DLK1 axis may represent a valuable target for the prevention and treatment of liver fibrosis." (PMID 35050550, 2022).
melanoma (2 papers, 2006 to 2017). A malignant, usually aggressive tumor composed of atypical, neoplastic melanocytes. "Noteworthy, the impairment of ECM invasion caused by PTTG1 knock-down was lower than that produced by dabrafenib, indicating that beside PTTG1 expression, additional pathways involved in melanoma cell invasiveness are inhibited by this drug." (PMID 29371923, 2017). "Notably, PTTG1 is one of the 17 gene-expression signature predicting metastasis and shorter survival in multiple tumor types and it is among the top-20 genes whose elevated expression was found to be associated with metastatic dissemination of melanoma." (PMID 29371923, 2017). "In that investigation we showed that PTTG1 silencing inhibited proliferation of melanoma cells and that the growth suppressive effects of the cyclin-dependent kinase (CDK) inhibitor PHA-848125 was in part dependent on drug-induced down-regulation of PTTG1." (PMID 29371923, 2017). "Here, we investigated the involvement of PTTG1 in melanoma cell proliferation, invasiveness and response to the BRAF inhibitor (BRAFi) dabrafenib." (PMID 29371923, 2017). "Our results provide evidence that PTTG1 is involved in the positive regulation of melanoma cell proliferation and invasiveness." (PMID 29371923, 2017). "Actually, MMP-9 plays an important role in melanoma invasion and PTTG1 has been shown to positively regulate the expression levels of MMP-9." (PMID 29371923, 2017). "We also preliminary assessed the potential value of circulating PTTG1 protein to monitor melanoma patient response to BRAFi or to dabrafenib plus trametinib." (PMID 29371923, 2017). "Previous investigations performed in cellular models different from melanoma, point out that PTTG1 expression can be regulated by multiple mechanisms." (PMID 29371923, 2017). "To investigate whether PTTG1 plays a role in melanoma cell proliferation, invasiveness and response to dabrafenib, we first examined its expression in A375, A375R, SK-Mel28 and SK-Mel28R cell lines exposed to 100 nM dabrafenib or to DMSO for 48 h." (PMID 29371923, 2017). "It has been previously shown that PTTG1 can promote tumor cell invasiveness by increasing the expression of several effector molecules, including MMP-9 which has been associated with an invasive phenotype in melanoma." (PMID 29371923, 2017). "PTTG1 is considered an oncogene, and it is over-expressed in a variety of cancer cell lines as well as in a wide range of primary and metastatic tumors, including melanoma." (PMID 29371923, 2017). "Indeed, it demonstrates that the PTTG1 protein was present in plasma of a considerable proportion of melanoma patients even though in different amounts." (PMID 29371923, 2017). "PTTG1 targeting might, therefore, represent a useful strategy to impair proliferation and metastasis of melanomas resistant to BRAFi." (PMID 29371923, 2017). "Although PTTG1 is over-expressed in melanoma specimens and is included in the gene panel identifying a metastatic behavior in this tumor, no data are available on the biological activity of the PTTG1 protein in melanoma cells, with exception of a previous study by our group." (PMID 29371923, 2017). "In this study we investigated the involvement of PTTG1 in the regulation of proliferation and invasiveness of melanoma cells sensitive or resistant to dabrafenib and whether targeting PTTG1 could affect the response of those cells to the BRAFi." (PMID 29371923, 2017). "Moreover, based on our results, we assessed whether changes of PTTG1 plasma levels occur in melanoma patients subjected to therapy with BRAFi or the combination of dabrafenib plus the MEK inhibitor (MEKi) trametinib." (PMID 29371923, 2017). "In the present study, we investigated the role of PTTG1 in melanoma cell proliferation, invasiveness and response to the BRAF inhibitor (BRAFi) dabrafenib by using two pairs of syngeneic melanoma cell lines sensitive or with acquired resistance to the drug." (PMID 29371923, 2017).
myelodysplastic syndrome (2 papers, 2008 to 2013). A clonal hematopoietic disorder characterized by dysplasia and ineffective hematopoiesis in one or more of the hematopoietic cell lines. "It has been reported that PTTG1 is overexpressed in samples from patients with hematopoietic neoplasms or myelodysplastic syndromes." (PMID 23977008, 2013).
neuroblastoma (2 papers, 2022 to 2025). Neuroblastoma (NB) is the most common solid, extracranial childhood tumor. "PTTG1 is an oncogene that is highly expressed in various cancers and is involved in regulating the cell cycle in neuroblastoma (NB) cells." (PMID 41264123, 2025). "After we knocked down PTTG1 in neuroblastoma cells, we showed that the number of cells in the G1 phase was also significantly increased." (PMID 35210406, 2022). "At the same time, we found that there was also a remarkable positive correlation between PCLAF and PTTG1 in three neuroblastoma databases." (PMID 35210406, 2022). "In this study, we reveal the mechanism by which PCLAF facilitates cell cycle progression and recommend that the PCLAF/E2F1/PTTG1 axis is a therapeutic target in neuroblastoma." (PMID 35210406, 2022). "Western blotting revealed that PTTG1 was expressed at higher levels in different neuroblastoma cell lines." (PMID 35210406, 2022). "In conclusion, we clarify the existence of the PCLAF/E2F1/PTTG1 axis, which has an imperative role in cell cycle progression in neuroblastoma cells." (PMID 35210406, 2022). "Our research found that PTTG1 is expressed at higher levels in neuroblastoma." (PMID 35210406, 2022). "However, additional mechanisms need to be explored, such as the specific mechanism by which PCLAF affects E2F1 expression and how PTTG1 affects neuroblastoma cell cycle progression." (PMID 35210406, 2022). "Subsequent mechanistic studies confirmed that PCLAF could stimulate the expression of PTTG1, affecting the G1-S transition of neuroblastoma cells." (PMID 35210406, 2022). "In addition, we analyzed the expression pattern of PTTG1 in neuroblastoma samples." (PMID 35210406, 2022). "At the same time, our analysis of neuroblastoma databases and clinical tissue samples confirmed that PCLAF showed a significantly positive correlation with PTTG1." (PMID 35210406, 2022). "Then we analyzed the relationship between PCLAF and PTTG1 genes and E2F1 in the neuroblastoma database and found that E2F1 was related to PCLAF and PTTG1." (PMID 35210406, 2022). "In addition, PCLAF can regulate the expression levels of PTTG1 through E2F1 and promote the proliferation of neuroblastoma cells." (PMID 35210406, 2022). "In addition, we found that diminishing the expression of E2F1 can reduce the protein and mRNA levels of PTTG1, which indicates E2F1 can alter PTTG1 expression in neuroblastoma by binding to the promoter of PTTG1." (PMID 35210406, 2022).
pancreatic adenocarcinoma (2 papers, 2023 to 2024). "The box plot generated from the analysis showed a significant increase in PTTG1 expression levels in pancreatic adenocarcinoma tissues (red) compared to matched normal tissues (gray)." (PMID 38465336, 2024).
papillary thyroid cancer (2 papers, 2013 to 2019). "We also evaluated the expression of PTTG1 by western blot on 6 MTC patients (a small representative number of patients), 2 controls (healthy thyroid), and 1 patient with papillary thyroid carcinoma (PTC), used as positive control (it has been reported to express elevated quantities of PTTG1)." (PMID 30911297, 2019).
pituitary apoplexy (2 papers, 2018 to 2022). A rare, potentially life-threatening disorder caused by acute ischemic infarction or hemorrhage in the pituitary gland. "No evident correlation was found between expression levels of MMP9, MMP2, TIMP2, and PTTG1 and clinical features of PAs, including gender, age, compression symptoms, pituitary apoplexy, tumor texture, resection degree, and recurrence." (PMID 36052250, 2022).
Rb (2 papers, 2021 to 2022). "The cells enriched in state-5 at the terminal of the branch shared a highly similar global expression profile with retinoblastoma cells that possess cell cycle (UBE2C, PTTG1, CCNB1) and proliferation (MKI67) properties." (PMID 34815392, 2021).
testicular tumors (2 papers, 2021 to 2022). "PTTG1 and its target MMP-2 were analyzed in human testicular tumors using the Atlas database." (PMID 33430117, 2021).
thyroid (2 papers, 2008 to 2013). "The postulated role of securin, the protein encoded by PTTG1, in thyroid tumorigenesis and in the development of hyperplastic lesions could be due to its overexpression during metaphase–anaphase transition, which could generate aneuploidy." (PMID 24145614, 2013). "From these observations, these investigators concluded that PTTG1 may promote tumor angiogenesis by regulating the expression of angiogenic genes such as VEGF, bFGF, ID3, and TSP-1, suggesting that PTTG1 may be a key gene in thyroid tumorigenesis." (PMID 19014669, 2008).
acute myeloid leukemia (1 paper, 2022). Acute myeloid leukemia (AML) is a group of neoplasms arising from precursor cells committed to the myeloid cell-line differentiation. "However, PTTG1 expression in acute myeloid leukemia (LAML) and testicular germ cell tumors (TGCT) was lower than that in normal tissues (all p < 0.01)." (PMID 35281830, 2022).
adrenal tumors (1 paper, 2020). "Increased expression of the nuclear protein in PTTG1 was observed in malignant adrenal tumors, and PTTG1 can serve as a biomarker for this tumor type." (PMID 33123466, 2020).
adult T-cell leukemia/lymphoma (1 paper, 2022). A peripheral (mature) T-cell neoplasm linked to the human T-cell leukemia virus type 1 (HTLV-1), adult T-cell leukemia/lymphoma is endemic in several regions of the world, in particular Japan, the Caribbean, and parts of Central Africa. "The KEGG pathway also showed that PTTG1 was linked to human T-cell lymphotropic virus type-1 (HTLV-1) infection, and HTLV-1 is a retrovirus that is closely related to adult T-cell leukemia/lymphoma (ATL)." (PMID 35281830, 2022).
bladder tumors (1 paper, 2022). "According to previous studies, PTTG1 is normally viewed as an oncogene, and high expression of PTTG1 can promote tumorigenesis in many kinds of tumors such as prostate and bladder tumors." (PMID 35281830, 2022).
cardiac hypertrophy (1 paper, 2020). "PTTG1 was a potential target of KLF10 in cardiac hypertrophy 6,21 but their relationship in MM remains unclear." (PMID 32549754, 2020).
Crohn disease (1 paper, 2025). A gastrointestinal disorder characterized by chronic inflammation involving all layers of the intestinal wall, noncaseating granulomas affecting the intestinal wall and regional lymph nodes, and transmural fibrosis. "The genotype frequencies (AA and AC) of rs2431697 in PTTG1 were 81% in the Qatari population; studies showed that these genotypes were associated with a decreased response to Infliximab in Crohn’s disease patients." (PMID 41346622, 2025).
diabetes (1 paper, 2021). "Pituitary tumor-transforming gene 1 (PTTG1) is a crucial factor in the development and physiological responses of pancreatic beta-cells, and its dysregulation can result in diabetes." (PMID 34516309, 2021).
endometrial cancer (1 paper, 2023). Primary or metastatic malignant neoplasm involving the endometrium (mucous membrane that lines the endometrial cavity). "In addition, among the genes closely associated with PPP1R14B expression, UBE2S, JPT1, and PTTG1 were associated with abnormal expression of endometrial cancer desiccations, proliferation, migration, methylation, and prediction of response to metformin therapy." (PMID 36824011, 2023).
endometriosis (1 paper, 2025). The growth of functional endometrial tissue in anatomic sites outside the uterine body. "PTTG1 is relatively unexplored in endometriosis, although it is known to be overexpressed in several tumors and implicated in various tumor processes." (PMID 40076450, 2025).
follicular thyroid carcinoma (1 paper, 2019). "Nonetheless, a possible implication of PTTG1 in the angiogenic process and in tumor progression has been noted in a follicular thyroid carcinoma model, such as a transgenic TRβPV mouse which spontaneously developed this tumor with distant metastases." (PMID 30911297, 2019).
glioblastoma (1 paper, 2025). The most malignant astrocytic tumor (WHO grade IV). "Another study supports this thesis by establishing that PTTG1 and TGF-β signaling appear to drive cellular behaviors characteristic of EMT in glioblastoma." (PMID 40072059, 2025). "PTTG1 enhances EMT by upregulating transcription factors such as Snail and Twist via TGF-β signaling, suppressing E-cadherin, and promoting invasiveness and metastasis while also modulating NF-κB signaling and tumor cell survival, particularly in aggressive cancers like glioblastoma and HCC." (PMID 40072059, 2025).
influenza (1 paper, 2020). An acute viral infection of the respiratory tract, occurring in isolated cases, in epidemics, or in pandemics; it is caused by serologically different strains of viruses (influenzaviruses) designated A, B, and C, has a 3-day incubation period, and usually lasts for 3 to 10 days. "For PTTG1, 1277 positively correlated genes connected with cell cycle, the metabolism of RNA, cellular responses to external stimuli, DNA repair, DNA replication, programmed cell death and protein localization as well as viral infection (HIV and influenza) were indicated." (PMID 32824814, 2020).
insulinoma (1 paper, 2014). "In addition, reporter luciferase assays in transfected BTC3 insulinoma cells overexpressing RasGrf1 documented the ability of RasGrf1 to modulate Pttg1 promoter activity through ERK-dependent signals." (PMID 25421944, 2014).
kidney cancer (1 paper, 2024). Primary or metastatic malignant neoplasm involving the kidney. "Remarkably, PTTG1 displayed heightened expression levels and showed an association with unfavorable prognosis among individuals diagnosed with kidney cancer." (PMID 39139816, 2024). "A number of studies have demonstrated that PTTG1 is an oncogene, and is overexpressed in various cancers, including breast cancer, colorectal cancer, lung cancer, and kidney cancer." (PMID 39139816, 2024).
Lymphatic Metastasis (1 paper, 2020). Transfer of a neoplasm from its primary site to lymph nodes or to distant parts of the body by way of the lymphatic system. "Besides, the patients with lymphatic metastasis showed higher PTTG1 mRNA levels than those in the patients without lymphatic metastasis (p < 0.05)." (PMID 32272902, 2020).
lymphocytic leukemia (1 paper, 2018). "Whether the effect of luteolin on lymphocytic leukemia cells is associated with PTTG1 expression remains unclear and needs to be further investigated." (PMID 29649138, 2018). "Several studies demonstrated that PTTG1 was also highly expressed in lymphocytic leukemia cell lines such as Jurkat and MOLT-4 cells." (PMID 29649138, 2018).
medullary thyroid cancers (1 paper, 2019). "Also, PTTG1 revealed a pathogenic role in papillary and medullary thyroid cancers, being overexpressed during the metaphase-anaphase transition." (PMID 30911297, 2019). "Given these premises on PTTG1 and AURKA involvement in thyroid tumorigenesis, we decided to explore their association and their prognostic significance in a large cohort of sporadic medullary thyroid cancer samples." (PMID 30911297, 2019).